FZD4 (frizzled class receptor 4)
Diseases named in the same sentence as FZD4 in open-access papers (continued):
Sharing a sentence is not in itself a finding about the gene and the disease.
Stroke (2 papers, 2021 to 2023). Sudden impairment of blood flow to a part of the brain due to occlusion or rupture of an artery to the brain. "In addition, therapeutic activation of FZD4 could also be beneficial in other vascular diseases of the CNS—such as stroke, traumatic brain injury, multiple sclerosis and Alzheimer’s disease—where endothelial cell barrier dysfunction is proposed to contribute to disease initiation and/or progression." (PMID 34105895, 2021).
acute myeloid leukemia (1 paper, 2023). Acute myeloid leukemia (AML) is a group of neoplasms arising from precursor cells committed to the myeloid cell-line differentiation. "Specifically in acute myeloid leukemia (AML), WNT10B signals through FZD4 and FZD5, while in T-cell acute lymphoblastic leukemia, WNT10B signals through FZD6." (PMID 36814601, 2023).
Autoimmunity (1 paper, 2023). The occurrence of an immune reaction against the organism's own cells or tissues. "FZD4-selective WNT surrogates potentially could find broader general application to additional conditions such as neurodegeneration, neoplasia, autoimmunity, and infection, representing neurological diseases at-large characterized by BBB dysregulation." (PMID 37268690, 2023).
bladder tumor (1 paper, 2021). "MiR-491-3p was also reported to directly target RhoC and FZD4 to suppress bladder tumor cell mobility." (PMID 33098307, 2021).
brain tumors (1 paper, 2022). "GRASP55 and GRASP65 have been shown to control the transport of proteins such as CD8α - a dendritic cell marker with increased expression in pro-inflammatory niches of brain tumors - and Frizzled-4 (FZD4), both containing valine residues at the C-terminal during Golgi trafficking." (PMID 35784465, 2022).
breast tumours (1 paper, 2012). "As components of the Wnt signalling pathway such as FZD7 and FZD4 are disrupted in many cancer types including colon, renal, brain and breast tumours, it is believed they promote the ability of the tumour to proliferate and invade the surrounding tissue." (PMID 22536405, 2012).
cardiac hypertrophy (1 paper, 2024). "This study revealed that EMPA treatment can alleviate TAC-induced cardiac hypertrophy by directly inhibiting the FZD4/Wnt/β-catenin/TCF7L2 pathway in cardiomyocytes." (PMID 39664517, 2024).
chronic myeloid leukemia (1 paper, 2022). "The relative mRNA expression levels of FZD4, FZD5, and FZD7 are upregulated in drug-mediated apoptotic chronic myeloid leukemia (CML) cells, suggesting a correlation with programmed cell death." (PMID 36452482, 2022).
coloboma (1 paper, 2018). An abnormality in which a part of a structure in one or both eyes is missing. "In examining the prioritized list of rare variants identified in superior coloboma patients, we note rare variants in NKD1, CELSR2, FZD4, SCRIB, and WNT9B (components of canonical or non-canonical Wnt pathways)." (PMID 29522511, 2018).
cortical dysplasia (1 paper, 2023). "SFRP1, LRP6, FZD4 and CTNNBIP1 genes showed very similar percentage delta CT values in control tissue and NAAC and with a difference in these delta values in tissue with cortical dysplasia." (PMID 37749503, 2023).
Crohn disease (1 paper, 2021). A gastrointestinal disorder characterized by chronic inflammation involving all layers of the intestinal wall, noncaseating granulomas affecting the intestinal wall and regional lymph nodes, and transmural fibrosis. "The role of FZD4 in EMT was first identified in patients suffering from penetrating Crohn’s disease, a common risk factor for CRC." (PMID 34604862, 2021). "Penetrating Crohn’s disease patients have elevated levels of WNT2b and FZD4, as well as n-cadherin and vimentin, suggesting FZD4 contributes to EMT in the colon." (PMID 34604862, 2021).
diabetes (1 paper, 2023). "In the gastrocnemius muscle, several genes involved in the Wnt signaling pathway were downregulated by diabetes, including Wnt2, Mpc1, Npnt, and Lrp6, whereas Fzd4 was higher in muscle from D mice." (PMID 38025035, 2023).
Duchenne muscular dystrophy (1 paper, 2024). Duchenne muscular dystrophy (DMD) is a neuromuscular disease characterized by rapidly progressive muscle weakness and wasting due to degeneration of skeletal, smooth and cardiac muscle. "Among this cohort of miRNAs, studies have illuminated the role of miR-199a-5p in Duchenne muscular dystrophy (DMD), where it influences the WNT signaling pathway via genes such as FZD4, JAG1, and WNT2, thereby impacting cellular proliferation and myogenic differentiation." (PMID 38600177, 2024).
endothelial dysfunction (1 paper, 2023). In vascular diseases, endothelial dysfunction is a systemic pathological state of the endothelium (the inner lining of blood vessels) and can be broadly defined as an imbalance between vasodilating and vasoconstricting substances produced by (or acting on) the endothelium. "FZD4 function therefore appears to be context and stimulus dependent – although it can play a homeostatic role, it also appears to promote endothelial dysfunction in ECs exposed to DF." (PMID 36846872, 2023). "To determine whether FZD4 mediates endothelial dysfunction under prolonged DF, we transfected ECs with siRNA targeting FZD4 before exposure to flow." (PMID 36846872, 2023).
hyperlipidemia (1 paper, 2018). "Dishevelled 2 (Dvl2) mRNA was declined in peri-implant bone tissue of high-fat (HF) group than normal group, while frizzled 4 (Fzd4) mRNA declined on day 5 and increased from day 10 to day 20 after implantation in hyperlipidemia rats than in normal rats." (PMID 30386554, 2018). "What is more, the expression of Fzd4 fluctuated in the normal and HF groups in vivo, and Fzd4 expression was significantly higher at the middle stage of osseointegration in hyperlipidemia rats than in normal rats." (PMID 30386554, 2018). "MiR-29a-3p/Dvl2/Fzd4 may serve as a promising therapeutic target for hyperlipidemia osseointegration." (PMID 30386554, 2018). "Moreover, we demonstrated that miR-29a-3p enforced osseointegration by targeting Dvl2 and Fzd4 in the Wnt/β-catenin pathway, and this enforcement could be impaired by hyperlipidemia." (PMID 30386554, 2018).
infertile (1 paper, 2017). "Moreover, FZD4 might have an important function for the corpus luteum and therefore progesterone production, because FZD4 ko mice are infertile." (PMID 28293067, 2017).
ischemic stroke (1 paper, 2023). A stroke disorder caused by obstruction of blood flow to the brain, due to thrombotic (local blood clot formation) or embolic (due to a blood clot or other material traveling from another site) event. "To expand the potential applications of FZD4-selective WNT surrogates beyond NdpKO mice to prevalent medical conditions, we investigated the effect of L6-F4-2 in adult ischemic stroke." (PMID 37268690, 2023).
lentivirus infection (1 paper, 2022). Virus diseases caused by the Lentivirus genus. "To examine the role of FZD4 in the osteogenic differentiation of BMSCs, we used a specific shRNA to silence FZD4 and used lentivirus infection to overexpress FZD4 transcripts." (PMID 35093173, 2022).
malignant glioma (1 paper, 2021). A grade III or grade IV glioma arising from the central nervous system. "In addition to its functions in promoting GSC stemness, studies have shown that WNT signaling indirectly promotes EMT in malignant glioma through its regulation of frizzled class receptor 4 (FZD4)." (PMID 34012965, 2021).
metastatic prostate carcinoma (1 paper, 2014). A carcinoma that arises from the prostate gland and has spread to other anatomic sites. "Inducible expression of FGFR1 in prostate epithelium led to formation of tumors that showed characteristics of EMT and had increased expression of SOX9 and Wnt pathway receptor frizzled 4 (Fzd4), both of which are expressed at high levels in human metastatic prostate cancer." (PMID 25277175, 2014).
metastatic tumors (1 paper, 2015). "WNT5A and WNT5B are ligands for and bound by FZD2 and FZD4, and this binding has been shown to drive EMT and is elevated in metastatic tumors." (PMID 26572553, 2015).
Obesity (1 paper, 2019). Accumulation of substantial excess body fat. "Consistent with the functional enrichment analyses, we identified hub genes related to blood vessel morphogenesis in the darkred module: TBXA2R, FZD4, COL15A1, and TBX2 were positively associated with maternal BMI and/or obesity and with birth weight." (PMID 31110514, 2019).
oral cancer (1 paper, 2020). "The LINC00319/miR-199a-5p/FZD4 axis, as a ceRNA network, is an important signaling pathway through which CCL18 regulates the proliferation, invasiveness, and angiogenesis of oral cancer cells." (PMID 32948745, 2020). "Importantly, the expression of miR-199a-5p and FZD4 were found to be mediated by CCL18, and miR-199a-5p mimics inhibited the CCL18-promoting effects in oral cancer cells." (PMID 32948745, 2020).
osteosarcoma (1 paper, 2021). A usually aggressive malignant bone-forming mesenchymal neoplasm, predominantly affecting adolescents and young adults. "FZD4 has been reported to promote Wnt/β-catenin signalling and markedly affect numerous neoplastic diseases, but there are few reports on the function of FZD4 in osteosarcoma." (PMID 34716310, 2021).
retinal edema (1 paper, 2025). "FZD4/LRP5 and FZD4/LRP6 agonists emerge as a class of agonists with potential uses in ME, but efficacy in preclinical mouse models of retinal edema remains to be demonstrated." (PMID 41086024, 2025).
triple-negative breast carcinoma (1 paper, 2019). An invasive breast carcinoma which is negative for expression of estrogen receptor (ER), progesterone receptor (PR), and human epidermal growth factor receptor 2 (HER2). "Intriguingly, Sox9 inhibition (whether transient or stable) resulted in significantly reduced expression of AXIN2, a classical Wnt/β-catenin target gene and of the Wnt receptor and target gene FZD4, in tamoxifen-resistant cells and in triple-negative breast cancer cells." (PMID 30622340, 2019).
viral infections (1 paper, 2021).
X-linked juvenile retinoschisis (1 paper, 2022). "These six SP variants were in the CRB1 (early-onset retinal dystrophy), NDP (familial exudative vitreoretinopathy) (FEVR), FZD4 (FEVR), EYS (retinitis pigmentosa), and RS1 (X-linked juvenile retinoschisis) genes." (PMID 36362148, 2022).
tumor (46 papers, 2007 to 2026). "Pathogenic variants of these genes were also identified, including tumor or posterior malformation in FZD4 (c.74G>T), ARRB2 (c.287A>C), and DACT1 (c.1561-1G>A) in humans and mice." (PMID 35008901, 2022). "Mechanically, we found the antitumor activity of Sja-miR-71a was through targeting a host gene encoding Frizzled Class Receptor 4 (FZD4), as FZD4 small interfering RNAs (siRNAs) generated a similar inhibitory effect on the tumor." (PMID 35174106, 2022). "Loss of vascular Norrin/Fzd4 signalling, either genetically or by short-term blockade, creates a tumor-permissive stroma that promotes the formation of preneoplastic lesions and their progression to malignancy." (PMID 27823583, 2016). "Loss of Norrin/Fzd4-mediated signalling in endothelial cells, either genetically or by short-term blockade, increases the frequency of pre-tumor lesions and creates a tumor-permissive microenvironment at the earliest, preneoplastic stages of MB." (PMID 27823583, 2016). "Together, these results show that loss of Norrin/Fzd4 signalling to endothelial cells accelerates the transition to a tumor-permissive stroma characterized by vascular permeability, inflammation and angiogenic remodelling." (PMID 27823583, 2016). "Using transgenic mice in which Foxf1 was deleted or overexpressed in endothelial cells, we found that FOXF1 inhibits lung tumor growth and metastasis and normalizes tumor-associated blood vessels by maintaining Wnt/β-catenin signaling in ECs through transcriptional activation of FZD4." (PMID 38589650, 2024). "Decreased tumor sizes in EEV-Fzd4-treated mice were associated with increased number of TECs expressing Fzd4 mRNA as demonstrated by RNAscope with probes specific to Fzd4, Foxf1, and Aplnr, the latter of which is a specific marker of general capillary cells in the lung." (PMID 38589650, 2024). "The Tie2Cre driver used to delete Fzd4 is also expressed in hematopoietic lineages, which, combined with our observation of leukocyte accumulation in Ndp/Fzd4-deficient lesions, leaves open the prospect of an immune cell-mediated component within the pro-tumor stroma." (PMID 27823583, 2016). "We xenografted different A549 cell lines into nude mice and found that A549 cells replenished with Fzd4 WT rapidly formed tumours, whereas A549 cells replenished with glycosylated mutants formed tumours at a slower rate or even failed to form tumours." (PMID 40230079, 2025). "At the same time, tumours formed by A549 cells replenished with Fzd4 WT grew significantly faster than tumours formed by A549 cells replenished with glycosylated mutants." (PMID 40230079, 2025). "HLF accelerates tumor growth and metastasis via modulation of frizzled-4 (FZD4) and forkhead box Q1 (FOXQ1)." (PMID 38545555, 2024). "Altogether, nanoparticle delivery of Fzd4 cDNA into endothelial cells of tumor-bearing endFoxf1+/− mice restored Fzd4 expression, increased nuclear β-catenin, improved endothelial basal membrane, and inhibited lung tumor growth." (PMID 38589650, 2024). "Fluorescently labeled PBAE nanoparticles with either CMV-Fzd4 (nano-Fzd4) or CMV-Empty (nano-Empty) plasmids were delivered intravenously to tumor-bearing mice one week after implantation of LLC tumor cells." (PMID 38589650, 2024). "This study supports the concept that increasing expression of FOXF1 or its downstream target FZD4 in tumor endothelial cells, either pharmacologically or via gene therapy, can be considered for NSCLC treatment." (PMID 38589650, 2024). "miR-493, as a tumor suppressor miRNA, suppresses cell motility by downregulating RhoC and FZD4 in BLCA." (PMID 39329952, 2024). "FZD4/5 are the key component proteins of wnt/β-catenin signaling, which play oncogenic roles in a variety of tumor types." (PMID 39735608, 2024). "Fzd4-positive CAFs was able to rescue tumor growth both in vitro and in vivo, indicating that Fzd4-mediated Lin28b expression in CAFs promotes PDAC growth." (PMID 37898598, 2023).
tumor (continued). "We found that AXIN1, CTNNB1 and LEF1 were highly expressed in tumor tissues and FZD4 was highly expressed in normal tissues in TCGA cohort." (PMID 36703749, 2022). "It was found that FZD4 level was increased while miR-671-5p level was reduced in NSCLC tumor samples." (PMID 36434577, 2022). "The phenotypes of the cells treated with FZD4 siRNAs were similar to those of Sja-miR-71a mimics-treated cells, suggesting that the FZD4 be the target gene of Sja-miR-71a and mediated anti-tumor effects." (PMID 35174106, 2022). "In GEO cohort, AXIN1 and LEF1 were highly expressed in tumor tissues, while FZD4 and FZD2 were highly expressed in normal tissues." (PMID 36703749, 2022). "Elevated circ_0017109 expression promotes tumor progression of NSCLC by modulating miR-671-5p/FZD4/β-catenin axis." (PMID 36434577, 2022). "The qPCR detection indicated both siRNA-737 and siRNA-1584 significantly reduced FZD4 expression in the tumor cell lines." (PMID 35174106, 2022). "Expectedly, HSPA4 overexpression increased the levels of HSPA4, HSPA5, CHOP, SDC-1, SDCBP-1, SOX4, FZD4, and β-catenin in tumor tissues, but 4-PBA inhibited the generation of these proteins." (PMID 35442158, 2022). "Collectively, hsa_circ_0004712 knockdown also limited tumor development in vivo by regulating miR-331-3p and FZD4." (PMID 34507595, 2021). "Downregulation of hsa_circ_0004712 also impaired tumor development in vivo by regulating miR-331-3p and FZD4." (PMID 34507595, 2021). "Numerous studies have shown that FZD4 is a direct downstream gene of several miRNAs (e.g., miR-SNP, miR-3127-5p, miR-516b, and miR-101) and participates in key mechanisms of tumor development." (PMID 32948745, 2020). "The presence of the FZD4-SNP in the 3′UTR down-regulated the ectopic expression of the host FZD4 gene and protein and inhibited tumor colony formation and tumor cell mobility in NSCLC cells." (PMID 28831115, 2017). "FZD4-SNP-3′UTR over-expression in H1299 cells showed a 50% reduction in tumor cell invasion compared with FZD-WT-3′UTR over-expression." (PMID 28831115, 2017). "Here, we modelled pre-tumor/stromal crosstalk during Ptch+/− MB evolution by manipulating the Norrin/Frizzled4 (Fzd4) pathway, an endogenous signalling axis that regulates vascular development in the cerebellum via neural/endothelial interactions." (PMID 27823583, 2016). "Finally, A549 cells supplemented with Fzd4 WT formed significantly heavier tumours than A549 cells supplemented with glycosylation mutants." (PMID 40230079, 2025). "In addition, since our data indicated that Wnt5a-Fzd4 pathway is essential for activation of Lin28b, we also tested the role of Fzd4 in tumor growth." (PMID 37898598, 2023). "We also performed WB using xenograft tumor tissues to analyze WNT/FZD4/β-catenin singling process." (PMID 36434577, 2022). "Moreover, we show that the anti-tumour effect of Norrin/Fzd4 signalling is restricted to the posterior region of the cerebellum and is characterized by defective neural progenitor migration away from the EGL." (PMID 35680976, 2022). "In addition to its immunomodulation and antifibrotic activities, Sja-mir-71a also inhibits the proliferation and migration of tumor cells through its interaction with the 3′-UTR region of the Frizzled Class Receptor 4 (FZD4) gene, reducing its expression." (PMID 35897749, 2022). "Prior researches have indicated that FZD4 may regulate the tumor microenvironment and the infiltration of immunocytes through the activation of Wnt/β-catenin pathway." (PMID 34801043, 2021). "In agreement with these consequences, we concluded that FZD4 was highly expressed in OC tissues and cells, and FZD4 overexpression reversed the anti-tumor effects of miR-331-3p, hinting that FZD4 was an oncogene in OC, which was consistent with the carcinogenic properties of FZD4 in other cancers." (PMID 34507595, 2021). "The anti-tumor effects of miR-331-3p restoration were reversed by FZD4 overexpression." (PMID 34507595, 2021).